PRSS58 (serine protease 58)
Synonyms: TRY1; TRYX3; UNQ2540
Tractability: Antibody: UniProt places it where antibodies can reach, with high confidence; UniProt predicts a signal peptide or a membrane-spanning region; its Gene Ontology location is reachable by antibodies, with medium confidence.
Gene: Protein-coding gene on chromosome 7 (142,252,143 to 142,258,058, reverse strand). Ensembl gene ENSG00000258223.
Subcellular location: Secreted
Gene Ontology:
Molecular function: serine-type endopeptidase activity
Biological process: protein maturation; positive regulation of reproductive process; proteolysis
Cellular component: secretory granule; extracellular region
Genetic constraint (gnomAD): Loss-of-function variants: 29 observed, 24.76 expected, observed/expected ratio (o/e) 1.17, 90% interval 0.87 to 1.59. The upper end of that interval is the gene's LOEUF score, 1.59, which puts it in group 6 of 6, group 1 being the genes least tolerant of losing a copy. Missense variants: 317 observed, 296.89 expected, observed/expected ratio (o/e) 1.07, 90% interval 0.97 to 1.17. Synonymous variants: 119 observed, 108.15 expected, observed/expected ratio (o/e) 1.1, 90% interval 0.95 to 1.28.
Homologues: Orthologues: chimpanzee PRSS58 (100% identical), macaque PRSS58 (97% identical), pig PRSS58 (74% identical), rabbit PRSS58 (72% identical), mouse Prss58 (66% identical), rat Prss58 (66% identical), guinea pig PRSS58 (60% identical), Drosophila melanogaster CG4477 (24% identical), Drosophila melanogaster CG3916 (22% identical), Drosophila melanogaster CG17477 (21% identical), Drosophila melanogaster CG32808 (21% identical), zebrafish hp (21% identical), and 7 more. Paralogues in human: KLK3 (32% identical), KLK5 (32% identical), KLK2 (32% identical), KLK8 (32% identical), KLK12 (31% identical), KLK11 (29% identical), KLK14 (29% identical), KLK1 (29% identical), KLK4 (29% identical), KLK7 (29% identical), TMPRSS4 (24% identical), PRSS54 (20% identical).